HERPUD1 (homocysteine inducible ER protein with ubiquitin like domain 1)
Description:
Component of the endoplasmic reticulum quality control (ERQC) system also called ER-associated degradation (ERAD) involved in ubiquitin-dependent degradation of misfolded endoplasmic reticulum proteins. Could enhance presenilin-mediated amyloid-beta protein 40 generation. Binds to ubiquilins and this interaction is required for efficient degradation of CD3D via the ERAD pathway.
Synonyms: HERP; KIAA0025; MIF1; SUP; HERPUD1-IT1
Tractability: Antibody: UniProt predicts a signal peptide or a membrane-spanning region. PROTAC: ubiquitination databases record sites on it; its protein half-life has been measured.
Gene: Protein-coding gene on chromosome 16 (56,930,815 to 56,944,864, forward strand). Ensembl gene ENSG00000051108.
Subcellular location: Endoplasmic reticulum membrane
Subcellular location (Human Protein Atlas): Cytosol; Plasma membrane
Pathways (Reactome):
Cellular responses to stimuli: ATF4 activates genes in response to endoplasmic reticulum stress
Gene Ontology:
Molecular function: protein binding; transmembrane transporter binding; ubiquitin-like ligase-substrate adaptor activity
Biological process: endoplasmic reticulum calcium ion homeostasis; ERAD pathway; negative regulation of endoplasmic reticulum stress-induced intrinsic apoptotic signaling pathway; negative regulation of intrinsic apoptotic signaling pathway; positive regulation of ERAD pathway; positive regulation of ubiquitin-dependent protein catabolic process; response to unfolded protein; retrograde protein transport, ER to cytosol; endoplasmic reticulum unfolded protein response; regulation of ERAD pathway; response to endoplasmic reticulum stress; ubiquitin-dependent protein catabolic process; intracellular calcium ion homeostasis; protein targeting to ER; regulation of endoplasmic reticulum stress-induced intrinsic apoptotic signaling pathway
Cellular component: endoplasmic reticulum; endoplasmic reticulum membrane; Hrd1p ubiquitin ligase complex; Lewy body core; membrane; endoplasmic reticulum quality control compartment
Genetic constraint (gnomAD): Loss-of-function variants: 16 observed, 36.43 expected, observed/expected ratio (o/e) 0.44, 90% interval 0.3 to 0.67. The upper end of that interval is the gene's LOEUF score, 0.67, which puts it in group 2 of 6, group 1 being the genes least tolerant of losing a copy. Missense variants: 404 observed, 475.54 expected, observed/expected ratio (o/e) 0.85, 90% interval 0.78 to 0.92. Synonymous variants: 157 observed, 174.77 expected, observed/expected ratio (o/e) 0.9, 90% interval 0.79 to 1.02.
Homologues: Orthologues: chimpanzee HERPUD1 (100% identical), macaque HERPUD1 (98% identical), dog HERPUD1 (91% identical), rabbit HERPUD1 (91% identical), pig HERPUD1 (90% identical), mouse Herpud1 (89% identical), guinea pig HERPUD1 (88% identical), rat Herpud1 (87% identical), tropical clawed frog herpud1 (45% identical), zebrafish herpud1 (43% identical), Drosophila melanogaster Herp (30% identical), Caenorhabditis elegans tag-353 (22% identical). Paralogues in human: HERPUD2 (39% identical).
Diseases named in the same sentence as HERPUD1 in open-access papers:
HERPUD1 is named in the same sentence as 64 diseases in open-access papers, as found by Europe PMC text mining. Sharing a sentence is not in itself a finding about the gene and the disease. The quoted sentences say what the papers report.
glioma (5 papers, 2017 to 2025). A benign or malignant brain and spinal cord tumor that arises from glial cells (astrocytes, oligodendrocytes, ependymal cells). "Herpud1 was regulated by miR-9-3p in glioma cells and tissues and was identified as a miR-9-3p target with luciferase reporter assays." (PMID 28430789, 2017). "In the present study, by using miRNA microarrays, we found decreased expression of miR-9-3p in glioma tissues and identified Herpud1 as the target of miR-9-3p." (PMID 28430789, 2017). "Glioma cells transfected with miR-9-3p mimics or HERPUD1-RNAi had more apoptotic cells than them in control after induced by H2O2." (PMID 28430789, 2017). "However, HERPUD1 promotes cell survival under endoplasmic reticulum stress conditions by inhibiting apoptosis in neurons and glioma cells." (PMID 40918139, 2025). "However, in neurons and glioma cells, HERPUD1 promotes cell survival under endoplasmic reticulum stress conditions by inhibiting apoptosis." (PMID 36544104, 2022). "Glioma may form a strategy of antioxidant stress by down-regulating miR-9-3p, thereby upregulating its target gene HERPUD1." (PMID 30379973, 2018). "MiR-9-3p enhanced H2O2 induced apoptosis through down regulation of Herpud1 in glioma cells." (PMID 28430789, 2017). "Our results suggested that miR-9-3p and its target Herpud1 may play an important role in the pathogenesis of glioma." (PMID 28430789, 2017). "Our results indicated that low expression of miR-9-3p results in a high level of Herpud1, which may protect against apoptosis in glioma." (PMID 28430789, 2017). "In these glioma tissues, expression of Herpud1 was increased compared with controls." (PMID 28430789, 2017). "We also examined the expression of Herpud1 in glioma tissues." (PMID 28430789, 2017). "The glioma might develop a strategy to protect against oxidative stress through down-regulating miR-9-3p and resulting in up-regulating its target gene Herpud1." (PMID 28430789, 2017). "Genes, such as OAS2, ULBP1, HERPUD1, and CASP4, are diagnosed with the growth of various cancers, such as oral cancer, cervical cancer, and gliomas, but these genes may identify with the development of BRCA." (PMID 31311202, 2019).
lung carcinoma (4 papers, 2019 to 2024). "The results of this study showed a better prognosis for patients with lung cancer that have high HERPUD1 expression." (PMID 37072786, 2023). "PRKCSH depletion promoted the interaction between HERPUD1 and IGF1R in lung cancer cells." (PMID 38200153, 2024).
ovarian carcinoma (4 papers, 2022 to 2025). A malignant neoplasm originating from the surface ovarian epithelium. "We use cBioPortal to determine the type and frequency of HERPUD1 gene mutations in ovarian cancer, based on the sequencing data of ovarian cancer patients in the TCGA database." (PMID 36544104, 2022). "In addition, the HERPUD1 gene mutation affects the prognosis of ovarian cancer, suggesting that HERPUD1 may be involved in the occurrence and development of ovarian cancer." (PMID 36544104, 2022). "In 34 cases of Early stage ovarian cancer tissue samples, 24 cases showed high expression of HERPUD1 and 10 cases showed low expression; 16 cases had high expression of Lewis y, and 18 cases had low expression." (PMID 36544104, 2022). "Through the MTT test, we found that knocking down HERPUD1 significantly reduced the proliferation ability of ovarian cancer cells (P < 0.05)." (PMID 36544104, 2022). "To further explore the target of HERPUD1 in ovarian cancer, we analyzed the kinase, miRNA, and transcription factor target networks of the positively related gene set generated by GSEA." (PMID 36544104, 2022). "The role and mechanism of HERPUD1 in ovarian cancer needs to be further studied in vivo in the future." (PMID 36544104, 2022). "HERPUD1 is highly expressed in ovarian cancer, especially in the early stage, and the expression of HERPUD1 and Lewis y antigen was positively correlated." (PMID 36544104, 2022). "We found that HERPUD1 expression in ovarian cancer cell lines(CAOV3, OVCAR3, SKOV3, ES-2) was higher than that in normal ovarian epithelial cells(H0SEpiC), and was highest in CAOV3 and SKOV3 cell lines." (PMID 36544104, 2022). "The results showed that the expression of HERPUD1 in ovarian cancer inhibited the occurrence of apoptosis and protected the survival of tumor cells, but not by activating Caspase12." (PMID 36544104, 2022). "After overexpression of Lewis y in ovarian cancer cells, and the expression of HERPUD1 protein also increased significantly (P < 0.05), indicating that the expression of HERPUD1 is regulated by Lewis y." (PMID 36544104, 2022). "Moreover, HERPUD1 has been shown to promote cytokine production and immune modulation in lung and ovarian cancer." (PMID 41193432, 2025). "In addition, HERPUD1 promotes the proliferation of ovarian cancer cells, inhibits apoptosis, affects the cell cycle, promotes the occurrence of autophagy, and inhibits EMT and PI3K/AKT/mTOR and p38MAPK pathways." (PMID 36544104, 2022). "Overall, HERPUD1, regulated by the expression of tumor-associated protein Lewis y, promotes cell survival in the early stages of tumors, suggesting that HERPUD1 may play an important role in the development of ovarian cancer." (PMID 36544104, 2022). "This study explored the role of HERPUD1 in ovarian cancer, its relationship with Lewis y, and related mechanisms through bioinformatics, clinical specimens, and cytology experiments, in order to provide new ideas for the research on ovarian cancer anticancer drugs." (PMID 36544104, 2022). "HERPUD1 overexpression in HeLa cells and ovarian cancer has been shown to reduce calcium flux from the ER while enhancing cell survival under stress, a phenotype that could be related to its role in lipid metabolism and explained its impact on the recently reported ER smooth expansion." (PMID 41193432, 2025). "Therefore, HERPUD1 is expected to become a new target for ovarian cancer chemotherapy." (PMID 36544104, 2022). "Based on the results of IHC and GEPIA website, we first proposed that the expression level of HERPUD1 was widely upregulated in ovarian cancer tissue samples, especially in the early FIGO stages, indicating that ovarian cancer may require higher levels of ERAD to maintain tumor survival." (PMID 36544104, 2022). "HERPUD1, an important early ERS marker, also promotes ovarian cancer cell survival by maintaining autophagy and inhibiting apoptosis through the PI3K/AKT/mTOR and p38 MAPK signaling pathways." (PMID 38711526, 2024).
ovarian carcinoma (continued). "The present study found that HERPUD1 may inhibit PI3K/AKT/mTOR pathway and p38MAPK pathway in ovarian cancer cells, thereby inducing autophagy and preventing the process of EMT." (PMID 36544104, 2022). "Moreover, HERPUD1 upregulation has also been reported in ovarian cancer tissues compared to non-malignant counterparts, suggesting a broader role for this protein in tumor biology." (PMID 41193432, 2025).
atherosclerosis (3 papers, 2022 to 2025). A disease characterized by the build-up of fatty material and calcium deposition in the arterial wall resulting in partial or complete occlusion of the arterial lumen. "Knockout of Herpud1 reduced Aβ1−40 expression other than lipid metabolism and alleviated atherosclerosis via JNK/AP1 signaling inhibition." (PMID 38918722, 2024).
prostate carcinoma (3 papers, 2016 to 2025). A carcinoma that arises from epithelial cells of the prostate gland. "For instance, in prostate cancer, lower HERPUD1 expression is associated with increased metastasis risk, and its overexpression rapidly induces apoptosis, suggesting a tumor-suppressive function." (PMID 41193432, 2025). "In addition, treatment of MM cells with GSK2606414 resulted in the upregulation of HERPUD1 gene expression, which is an ER stress responsive gene that was previously connected to reduced tumor-associated expression in prostate cancer cells." (PMID 33028016, 2020). "The differentially expressed gene-list contained various genes previously reported to be differentially expressed in low- and intermediate/high-grade prostate cancer such as HOXC6, MAGEC2, HERPUD1 and SATB1." (PMID 27191985, 2016).
viral infection (3 papers, 2020 to 2026). "In the acute phase of viral infection (4 hpi; cluster 2), genes responsive to ER stress, such as HSPA1A, HSPA5, and HERPUD1, were specifically upregulated, suggesting that viral infection affects cellular phenotypes from the early hours after cellular entry." (PMID 33142113, 2020).
breast carcinoma (2 papers, 2024 to 2025). "To address these possibilities, we first analyzed HERPUD1 expression in breast cancer (BC) biopsies via immunohistochemistry and immunofluorescence, revealing significantly higher levels in BC, including luminal A and TNBC, compared to non-malignant tissue." (PMID 41193432, 2025). "Altogether, our results indicate that HERPUD1 is overexpressed in breast cancer tissues, including both luminal A and TNBC subtypes, compared to NBT." (PMID 41193432, 2025). "Given the established link between cancer and cellular stress, we explored the role of HERPUD1 in breast cancer (BC) by analyzing its expression in non-malignant breast tissue (NBT), luminal A, and TNBC biopsies." (PMID 41193432, 2025). "The roles of the DNAJB9, CHAC1, HERPUD1 genes in senescence induction have not been reported but these genes are all involved in tumorigenesis in breast cancers." (PMID 39466820, 2024).
cardiac hypertrophy (2 papers, 2017 to 2020). "Taken together, the results show that a Herpud1 deficiency leads to the development of cardiac hypertrophy and impaired myocardial function." (PMID 29042597, 2017). "Herpud1 inhibition has recently been associated with induced pathological cardiac hypertrophy, which could explain the reduced hypertrophy observed in NLRP3 −/− mice." (PMID 31625260, 2020). "In agreement with the development of cardiac hypertrophy, cardiomyocyte cross-sectional area was significantly increased in Herpud1 silenced mice." (PMID 29042597, 2017). "Deletion or reduction of this protein induces cardiac hypertrophy both in vivo and in vitro, indicating the importance of Herpud1 in maintaining basal homeostasis as well as suggesting a potential role in anti-hypertrophic mechanisms." (PMID 29042597, 2017). "Our results show that Herpud1-knockout mice exhibit cardiac hypertrophy and dysfunction and that decreased Herpud1 protein levels lead to elevated levels of hypertrophic markers in cultured rat cardiomyocytes." (PMID 29042597, 2017). "The goal of this study was to elucidate the role of Herpud1 in cardiac pathophysiology and to assess whether Herpud1 might serve as a novel therapeutic target in pathological cardiac hypertrophy." (PMID 29042597, 2017). "Herpud1 is a novel negative regulator of pathological cardiac hypertrophy." (PMID 29042597, 2017). "We hypothesize that Herpud1 acts as a negative regulator of cardiac hypertrophy by regulating IP3R protein levels." (PMID 29042597, 2017).
cervical carcinoma (2 papers, 2019 to 2022). A carcinoma arising from either the exocervical squamous epithelium or the endocervical glandular epithelium. "The next biomarker is cg05713971 near an effective gene called HERPUD1 Antineoplastic activity has been shown to be associated with gene HERPUD1 and further related to human cervical carcinoma according to a recent in vitro experiment." (PMID 36249027, 2022).
lung adenocarcinoma (2 papers, 2023 to 2025). A carcinoma that arises from the lung and is characterized by the presence of malignant glandular epithelial cells. "Our study identified a novel m6A-related ferroptosis-associated six-gene signature (comprising SLC2A1, HERPUD1, EIF2S1, ACSL3, NCOA4, and CISD1) for predicting lung adenocarcinoma prognosis, yielding a useful prognostic biomarker and potential therapeutic target." (PMID 37072786, 2023). "Similarly, in lung adenocarcinoma (LUAD), HERPUD1 is downregulated in tumor tissues, where its low expression is associated with poor prognosis." (PMID 41193432, 2025).
melanoma (2 papers, 2017). A malignant, usually aggressive tumor composed of atypical, neoplastic melanocytes. "Another down-stream target of the IRE1 pathway, HERPUD1, showed even better prognosis for melanoma patients when it was highly-expressed." (PMID 29235576, 2017). "Although HERPUD1, INSIG1 and MMS22L were mutated in more than one of the melanoma cell lines, only Ma-Mel-86a cells were recognized by the respective T cell clones." (PMID 28423700, 2017).
metabolic syndrome (2 papers, 2016 to 2022). A cluster of metabolic risk factors for CARDIOVASCULAR DISEASES and TYPE 2 DIABETES MELLITUS. "Interestingly, variants in HERPUD1 have been associated with the metabolic syndrome in GWAS." (PMID 27738493, 2016). "For instance, ZPR1 and BUD13 were well-documented for lipid level, HERPUD1 was found related to HDL-C in the Korean population, and the APOA5 and CETP also showed evidence of contributing to triglycerides, metabolic syndrome, and HDL-C." (PMID 35238325, 2022).
cardiomyopathy (1 paper, 2023). A disease of the heart muscle or myocardium proper. "Genes associated with ER stress (e.g., ATF4, NUPR1, DDIT3, TRIB3, CHAC1, SESN2, HERPUD1) were upregulated and genes related to cardiomyopathy and sarcomeric structure (e.g., MYH7, SYNPO2L, LDB3, ACTN2, MYLK3) were downregulated by afatinib, sorafenib, or high-dose ponatinib." (PMID 37069550, 2023).
choroidal neovascularization (1 paper, 2024). An eye disorder described by the growth of new blood vessels that originate from the choroid through a break in the Bruch membrane into the sub–retinal pigment epithelium (sub-RPE) or subretinal space. "Herpud1, upregulated in IL-4-treated macrophage, promoted their migration, and, in a mouse model of choroidal neovascularization (CNV), it promoted M2 macrophage polarization, favoring the development of CNV." (PMID 39453673, 2024).
clear cell carcinoma (1 paper, 2022). "Among the pathological types, the high expression rate of HERPUD1 in endometrioid group was significantly higher than that of the serous group, clear cell carcinoma group and poorly differentiated adenocarcinoma group (P = 0.001, 0.011, 0.023)." (PMID 36544104, 2022).
emphysema (1 paper, 2021). "Our results suggest that smoking and emphysema increase GRP78 and HERPUD1 protein levels in ATII cells." (PMID 34356843, 2021). "GRP78 mRNA levels were lower in emphysema patients than in non-smokers and smokers, and HERPUD1 expression was decreased in patients with this disease compared to non-smokers." (PMID 34356843, 2021). "Moreover, both GRP78 and HERPUD1 levels were higher in emphysema patients than non-smokers, as detected by Western blotting." (PMID 34356843, 2021). "Furthermore, we determined GRP78 and HERPUD1 protein levels in ATII cells isolated from non-smokers, smokers, and emphysema patients." (PMID 34356843, 2021).
endometrial cancer (1 paper, 2023). Primary or metastatic malignant neoplasm involving the endometrium (mucous membrane that lines the endometrial cavity). "Studies have reported that HERPUD1 overexpression can promote apoptosis of various cancer cells (e.g., gastric, prostate, and endometrial cancer) induced by endoplasmic reticulum stress." (PMID 37072786, 2023).
endophthalmitis (1 paper, 2021). An infectious process affecting the internal structures of the eye. "Except Herpud1 siRNA, L002 and STF‐083010 administrated via intraperitoneal injection is better than intravitreal injection to some extent, as it avoids ocular complications such as ocular hypertension and endophthalmitis." (PMID 34057287, 2021).
Flavivirus Infections (1 paper, 2021). Infections with viruses of the genus FLAVIVIRUS, family FLAVIVIRIDAE. "However, further studies are required to confirm role of HERPUD1 in innate immune response evasion by flavivirus infection." (PMID 33500388, 2021).
gastric cancer (1 paper, 2022). A primary or metastatic malignant neoplasm involving the stomach. "A previous study showed that Circ_002117 upregulated HERPUD1 through miR-370 binding to increase the apoptosis of gastric cancer cells induced by ER stress." (PMID 36038536, 2022).
Hepatomegaly (1 paper, 2017). Abnormally increased size of the liver. "Finally, these findings support a larger scale screening for HERPUD1 R50H and HFE H63D variants in the sub-group of 1ATD patients developing significant chronic hepatic injuries (hepatomegaly, chronic cholestasis, elevated liver enzymes) and at risk developing liver cirrhosis." (PMID 28617828, 2017).